ABCG2 (ATP binding cassette subfamily G member 2 (JR blood group))
Diseases named in the same sentence as ABCG2 in open-access papers (continued):
Sharing a sentence is not in itself a finding about the gene and the disease.
breast cancer (continued). "Another rotenoid, boeravinone, reverses drug resistance by blocking BCRP/ABCG2-triggered drug efflux in breast cancer cells, and 6-deoxyclitoriacetal also showed excellent anti-tumor activity in SW620, KATO, ChaGo, BT474 and HepG2 cells." (PMID 28548956, 2017). "Further, ABCC1 and ABCG2 are highly expressed in core basal subtype, which is one of the most aggressive breast cancer subtypes, while ABCC11 is highly expressed in the HER2 or core basal subtypes." (PMID 28912626, 2017). "In this study, we examined the genotype frequencies of ABCB1 C3435T and ABCG2 C421A distribution in Chinese female breast cancer patients and healthy controls." (PMID 29340035, 2017). "A variety of drug-loaded nanoparticles conjugated with antibodies to these markers (CD44, CD133, and ABCG2) have been developed that improve the drug delivery efficiency to CSCs in colon cancer, breast cancer, and multiple myeloma." (PMID 28400729, 2017). "We also detected ABCB1 C3435T and ABCG2 C421A genotypes in the cancerous and normal tissues from breast cancer patients." (PMID 29340035, 2017). "ABCG2 was initially cloned from multidrug-resistant breast cancer cell lines and demonstrated to confer resistance to chemotherapeutic agents such as mitoxantrone, topotecan, and SN-38." (PMID 28880238, 2017). "As cisplatin increased the canonical Wnt7b in the study, increase of ABCB1 and ABCG2 perhaps is not surprising as previous studies have also demonstrated beta-catenin dependent induction of ABCB1 in breast cancer and ABCG2 in colon cancer." (PMID 28340578, 2017). "A recent study has reported that berberine decreased the proportion of side-population (SP) cells in breast cancer and reversed drug resistance by inhibiting ABCG2 protein expression." (PMID 27338343, 2016). "Other reports showed that ABCC1, ABCC11 and ABCG2 are highly over-expressed in subtypes of aggressive breast cancer and that increased expressions of ABCC1 and ABCC11 were significantly associated with shorter disease-free survival." (PMID 26883574, 2016). "In breast cancer, multidrug resistant proteins ATP-binding cassette transporters, ABCC1 and ABCG2, export S1P after estrogen stimulation of breast cancer cells." (PMID 26966342, 2016). "Our three bisulfite PSQ methods were applied to determine the promoter methylation levels of ABCB1, ABCC1 and ABCG2 in biopsy samples from 16 breast cancer patients." (PMID 27689338, 2016). "Breast cancer resistance protein (BCRP/ABCG2) was initially discovered in multidrug resistant breast cancer cell lines, where it confers resistance to several chemotherapeutic agents." (PMID 27834829, 2016). "Isoliquiritigenin has been shown to augment chemosensitivity by targeting the β-catenin-mediated induction of ABCG2 in breast cancer." (PMID 27776341, 2016). "Among ABC transporter family members, a novel protein, the breast cancer resistance protein (ABCG2), has been detected in a variety of malignancy tumors, such as breast cancer." (PMID 26575421, 2015). "Curcumin sensitized breast cancer cells to chemotherapeutic drugs by reducing the BCSC population mainly through a reduction in the expression of ABCG2." (PMID 26305906, 2015). "After intravenous injection of PEAL NPs in tumor-bearing mice, the ABCG2-siRNA-loaded NPs with UTMD efficiently silenced the ABCG2 gene and enhanced the ADR susceptibility of MCF-7/ADR (ADR resistant human breast cancer cells)." (PMID 26575421, 2015). "To deliver ABCG2-siRNA effectively into breast cancer cells, we used mPEG-PLGA-PLL (PEAL) nanoparticles (NPs) with ultrasound-targeted microbubble destruction (UTMD)." (PMID 26575421, 2015). "The overexpression of the breast cancer resistance protein (ABCG2) confers resistance to Adriamycin (ADR) in breast cancer." (PMID 26575421, 2015). "ABCG2/BCRP was initially isolated from drug-resistant breast cancer cells and is a key factor in determining drug absorption, distribution, and elimination." (PMID 26305906, 2015).
breast cancer (continued). "BCRP, which is a transmembrane protein encoded by the ABCG2 gene, was originally isolated from adriamycin-resistant breast cancer cell lines (MCF-7/AdrVp)." (PMID 25854646, 2015). "Other studies suggested that ABCG2 alone can be considered a suitable marker for breast cancer, in particular for TNBC phenotype, but this observation was limited to cellular models." (PMID 26504780, 2015). "Another ABC transporter capable of inducing drug resistance in breast cancer cells was termed ABCG2." (PMID 26319434, 2015). "One report describes the reversal of methotrexate, mitoxantrone, and paclitaxel resistance due to sildenafil-mediated downregulation of ABCG2 and P-gp in breast cancer cells." (PMID 26714461, 2015). "To confirm the prognostic values of ENPP1 and ABCG2 expression in other types of cancer, we examined the expression levels of these mRNAs in luminal B and basal-type breast cancer samples." (PMID 26065921, 2015). "ABCG2 was first discovered in a breast cancer cell line, which is also called breast cancer resistance protein (BCRP/ABCG2)." (PMID 26149077, 2015). "The resensitization effects of breast cancer towards ADR after ABCG2-siRNA transfection and in vivo safety of siRNA-loaded PEAL NPs were also investigated." (PMID 26575421, 2015). "Many studies have been reported down-regulated ABCG2 expression and reverse drug resistance in breast cancer." (PMID 26575421, 2015). "Other studies have also observed this switch through the interconversion of CD44− in CD44+ prostate cancer cells and ABCG2− in ABCG2+ breast cancer cell as a result of microenvironmental changes." (PMID 26452033, 2015). "Among three human breast cancer cell lines ABCG2 and COX-2 were highly expressed in MCF7-MX and MDA-MB-231 cells, respectively." (PMID 25587329, 2014). "ABCG2 (ATP-binding cassette, sub-family G, member 2; also known as BRCP, breast cancer resistance protein) is a member of the ABC transporter family that was originally found to confer drug resistance in breast cancer cells." (PMID 24782769, 2014). "Herein, we revealed that the natural chalcone-type compound ISL aggravated autophagy in drug-resistant breast cancer cells, which was accompanied by a G2/M checkpoint arrest and the downregulation of ABCG2 expression." (PMID 25026296, 2014). "The breast cancer resistance protein (BCRP or ABCG2) is an ABC transporter that was originally identified in doxorubicin-resistant breast cancer cells." (PMID 25226504, 2014). "ABCG2 was first discovered in breast cancer cell line MCF-7, where it became resistant to DOX (MCF-7/AdrVp)." (PMID 25268163, 2014). "The present study aimed to examine the relationship between the inhibition of COX-2 and expression of ABCG2 in parental and resistant breast cancer cell lines." (PMID 25587329, 2014). "CD147 can form a complex with ABCG2 on the cell membrane in primary effusion lymphoma and breast cancer cells, as determined by co-immunoprecipitation." (PMID 25268615, 2014). "In the study by Britton and colleagues with both clinical fine needle aspirates obtained from breast cancer patients as well as established breast cancer cell lines, the expression of ATP-binding cassette sub-family G member 2 (ABCG2=BCRP1) was monitored." (PMID 25051360, 2014). "To strengthen our conclusions, we next assessed the consequences of ABCG2 depletion on stemness properties of HCC1937 breast cancer cells by performing mammospheres formation assays." (PMID 25216750, 2014). "Here, we have identified an additional reliable antigen, CD338/ABCG2, that can be used to refine the sorting of the luminal progenitor subpopulations of BRCA1-mutated breast cancer cells." (PMID 25216750, 2014). "Immunofluorescence detection revealed that ISL increased the LC3-II expression in breast cancer tissue but decreased the expression of ABCG2, indicating that the chemosensitizing effects of ISL in vivo were closely connected to autophagy induction." (PMID 25026296, 2014).
breast cancer (continued). "BCRP, also known as ABCG2, took its name from the multidrug resistant breast cancer cell line co-selected for doxorubicin and verapamil resistance from which it was isolated." (PMID 24351843, 2013). "Its role in breast cancer is still fairly discussed, although recent lines of evidence have indicated ABCG2 as a potential stemness marker also in this neoplasia." (PMID 23976904, 2013). "As for miR-328, its expression was found to be inversely correlated to ATP-binding cassette subfamily G(ABCG2) levels in human breast cancer cells." (PMID 24339958, 2013). "Recent data showed that knock-down of ABCG2 inhibited breast cancer and lung cancer cells proliferation, suggesting the role of ABCG2 in maintenance the cancer cells." (PMID 23153066, 2012). "ABCG2, which is a member of ATP-binding cassette transporters, has been recently reported as a target gene for miR-328 in breast cancer cell lines." (PMID 22453125, 2012). "Intriguingly, three members of the ATP-binding cassette (ABC) transporter family (ABCA5, ABCC5, ABCG2) were overexpressed in breast cancer bone metastases compared with primary tumors that are metastatic to bone." (PMID 23174366, 2012). "The large variations of intra- and inter-groups ABCG2 expression observed in this study had also been reported in acute leukemia, breast cancer and lung cancer." (PMID 23153066, 2012). "ABCG2 was first identified in doxorubicin-resistant human MCF-7 breast cancer cells and thus also named as breast cancer resistance protein (BCRP)." (PMID 22209971, 2012). "A recent study showed that aryl hydrocarbon receptor (Ahr) is a direct transcriptional activator of ABCG2 in breast cancer." (PMID 23144836, 2012). "In the current paper we describe a novel pharmacological lethal Trojan horse strategy to differentially kill MDR breast cancer cells via photoexcitation of photosensitizer anticancer drugs that highly accumulated in ABCG2-rich EVs." (PMID 22530032, 2012). "Intriguingly, several members of the ATP-binding cassette (ABC) transporter superfamily (ABCA5, ABCC5, and ABCG2) were consistently overexpressed in breast cancer bone metastases compared with primary breast tumors." (PMID 23174366, 2012). "ABCG2, also called breast cancer resistant protein, was first discovered in doxorubicin-resistant breast cancer cells, and it predominantly localizes to the plasma membrane." (PMID 23189181, 2012). "So, it is interesting to explore the expression of these two potential prognostic bio-markers, HIF-2a and ABCG2, and their possible correlations in primary breast cancer." (PMID 22452996, 2012).
breast cancer (continued). "The IHC expression and distribution of ABCG2 in invasive breast cancer cells are as same as the findings of our previous study." (PMID 22452996, 2012). "MiR-328 influences drug disposition in human breast cancer cells by downregulation a gene ABCG2 that has been found to be highly expressed in SP cells." (PMID 22453125, 2012). "Similar results were obtained with ABCG2-overexpressing flavopiridol-resistant breast cancer cells (MCF-7/FLV1000) which differ from MCF-7/MR cells in their subcellular localization of ABCG2 and frequency of EVs formation." (PMID 22530032, 2012). "Taking advantage of the photosensitizer nature of IAs we examined their intravesicular accumulation in mitoxantrone-resistant breast cancer cells (MCF-7/MR) that overexpress ABCG2 exclusively at the membrane of EVs." (PMID 22530032, 2012). "It is not disappointing, because previous studies have showed that the effects of E2 on ABCG2 expression in breast cancer cells were inconsistent and tissue-specific as a result of the differences between ERαand ERβ." (PMID 21943250, 2011). "Previously we have shown that ABCG2-rich EVs of breast cancer cells concentrate riboflavin and MR by factors of 560- and 1000-fold, respectively, when compared to their concentration in the extracellular medium." (PMID 21283667, 2011). "The PTEN and Akt pathway has recently been implicated in maintaining the SP phenotype in glioma stem cells and breast cancer stem cells, probably through affecting the activity of ABCG2." (PMID 21526180, 2011). "Recently we have shown that overexpression of ABCG2 in the membrane of novel extracellular vesicles (EVs) in breast cancer cells results in mitoxantrone resistance due to its dramatic sequestration in EVs." (PMID 21283667, 2011). "The phenomenon of reversal of differentiation was not only exhibited with the altered expression of CD44/CD24 surface markers during culture but was also noticed in altered expression of ABCG2 in breast cancer cells." (PMID 21935375, 2011). "But little is known about the contribution of ABCG2 to the drug resistance and the clinicopathological characteristics in breast cancer." (PMID 21943250, 2011). "The existence of EVs in tumor cells other than the MCF-7/MR breast cancer subline was previously identified in our recent paper with the ABCG2-overexpressing non-small lung cancer A549/K1.5 cells." (PMID 21283667, 2011). "ABCG2+ side population (SP) breast cancer cells are strongly resistant to chemotherapeutic drugs, and these CSC-like cells are highly tumorigenic." (PMID 21072210, 2010). "ABCG2 expression in cancer cells has been shown to confer a drug-resistant phenotype and correlates with response to anthracyclines in breast cancer." (PMID 19432961, 2009). "These side population cells have been identified in breast cancer cell lines of luminal type, and these cells overexpress transporter genes ABCG2 (ATP-binding cassette, subfamily G, member 2) and ABCA3 (ATP-binding cassette, subfamily A, member 3)." (PMID 17062128, 2006). "More recently, other members of this family have been implicated in multidrug resistance of breast cancer, such as BCRP/ABCG2 and other forms." (PMID 16434992, 2006). "The upregulation of ATP citrate lyase (ACLY) increases the expression of the resistant proteins such as ABCB1/ABCG2, making breast cancer cells resistant to docetaxel, thereby suggesting ACLY as a potential predictive biomarker of tumor recurrence in breast cancer." (PMID 40843360, 2025). "To further confirm the functional role of NRF2 in regulating ABC transporter expression, we next conducted chromatin immunoprecipitation analysis of NRF2, akin to studies reported for ABCC1 and ABCG2 in human lymphoid cells, breast cancer, lung cancer and prostate cancer cells." (PMID 41372143, 2025).
breast cancer (continued). "Following the identification of ABCB1 and ABCC1, ABCG2 (also known as BCRP/MXR) was discovered in mitoxantrone-resistant human colorectal cancer cells and anthracycline-resistant breast cancer cells, and has since been shown to mediate the efflux of a broad spectrum of anticancer agents." (PMID 40806557, 2025). "Similarly, in MDA-MB-231 breast cancer cells, increasing levels of ABCG2 in EVs, concomitant with decreasing levels of this protein in the cells of origin, were observed." (PMID 38612927, 2024). "In addition, studies have shown the functional relevance of ATP binding cassette subfamily G member 2 -ABCG2 (also known as BCRP, a breast cancer resistance protein) in relation to CSCs and therapeutic response." (PMID 38787133, 2024). "In addition, Shimizu demonstrated that PDZK1 physically binds with ABCG2 and regulates breast cancer resistance." (PMID 38669103, 2024). "BCRP/ABCG2, responsible for mediating camptothecin’s effects and contributing to the bystander effect observed with T-DXd, is upregulated in metastatic compared to primary breast cancer, among other types." (PMID 38794221, 2024). "In addition, hsa-miR-328 controls the PTGR of ABCG2 in the drug-resistant breast cancer cells to modulate mitoxantrone sensitivity." (PMID 39114355, 2024). "It was reported that miRNA-328 may decrease chemoresistance in glioblastoma cancer cells and breast cancer cells by down-regulating the ABCG2 gene." (PMID 36769265, 2023). "Another study revealed that nuclear translocation of EGFR is regulated by AKT, which is associated with gefitinib resistance in breast cancer cells through enhanced gene expression of the breast cancer-resistant protein (BCRP; also known as ATP-binding cassette subfamily G member 2, ABCG2)." (PMID 37461111, 2023). "The results of our study suggest that miR‐548 K may be involved in modulating the expression of ABCG2 in MDR breast cancer cells." (PMID 37166017, 2023). "MiR‐548 k likely acts as an inhibitory factor of ABCG2 transcript in breast cancer cells." (PMID 37166017, 2023). "The expression of ABCG2 protein is correlated with the expression of HER2 in breast cancer, suggesting that ABCG2 is not only a drug-resistance-related transporter but also a potential biomarker predicting the biological behaviour, clinical progression and prognosis of breast cancer." (PMID 37445716, 2023). "MiR-99a-5p sensitized breast cancer cells to doxorubicin by regulating the COX-2/ABCG2 axis." (PMID 37508580, 2023). "Importantly, ABCB1/ABCG2 inhibitor dofequidar improved therapy responses in a subset of breast cancer patients." (PMID 37147730, 2023). "Fourteen microRNAs were determined, which may probably be involved in breast cancer drug resistance mediated by ABCG2." (PMID 37166017, 2023). "The results of our study suggested that miR‐548 K may be involved in regulating the expression of ABCG2 in breast cancer cells." (PMID 37166017, 2023). "An overexpression of ABCG2 has been found in drug resistant breast cancer tumor cells." (PMID 37092084, 2022). "The ABCG2 protein is highly expressed in several chemoresistant breast cancer cell lines." (PMID 35563449, 2022). "Many reviews have been published up till now discussing the importance of mdr1 and ABCG2 genes but the results have been contrasting regarding its association with breast cancer and no data is available in Pakistani population." (PMID 37092084, 2022). "Most of the studies on these genes have evaluated the effect of mutations with particular drug therefore this research is important in providing a clear picture of genetic and expression status of mdr1 and ABCG2 genes in breast cancer before any drug was administered." (PMID 37092084, 2022). "For example in the breast cancer cell line MCF7 SP it was shown that MCF7 SP abundance could be depleted by TGF- β1 directed EMT and that this was associated with a decrease in ABCG2 expression." (PMID 35118633, 2022).